MIR452 (microRNA 452)
Synonyms: hsa-mir-452; MIRN452; mir-452
Gene: MicroRNA gene on chromosome X (151,959,628 to 151,959,712, reverse strand). Ensembl gene ENSG00000283751.
Gene Ontology:
Biological process: miRNA-mediated post-transcriptional gene silencing
Cellular component: RISC complex
Homologues: Orthologues: chimpanzee ptr-mir-452 (100% identical), macaque MIR452 (100% identical), rabbit MIR452 (100% identical), guinea pig MIR452 (99% identical), dog MIR452 (98% identical), pig ssc-mir-452 (89% identical).
Diseases named in the same sentence as MIR452 in open-access papers:
MIR452 is named in the same sentence as 4 diseases in open-access papers, as found by Europe PMC text mining. Sharing a sentence is not in itself a finding about the gene and the disease. The quoted sentences say what the papers report.
colitis (1 paper, 2019). Inflammation of the colon. "In our previous study, MIR452 was found to be upregulated in both CRC and colitis by differential miRNA expression profiling of human CRC tissues and dextran sulfate sodium (DSS)-induced mouse colitis tissues, respectively." (PMID 31652600, 2019).
hepatocellular carcinoma (1 paper, 2019). A malignant tumor that arises from hepatocytes. "Several studies have suggested that MIR452 expression is downregulated in human breast cancer, glioma, and hepatocellular carcinoma (HCC)." (PMID 31652600, 2019). "However, in other studies, MIR452 has been found to be upregulated in hepatocellular carcinomas and lymph node-positive urothelial carcinomas, suggesting that MIR452 can have diverse roles in distinct types of human cancers or cells." (PMID 31652600, 2019).
tumor (1 paper, 2019). "To study the effect of MIR452 on tumor growth in vivo, we used a xenograft tumor model consisting of athymic nude mice with subcutaneously implanted HT29 cells." (PMID 31652600, 2019). "Collectively, our results suggested that downregulation of VEGFA expression by increased MIR452 levels in CRC tissues and cells might act as an early inhibitory mechanism against tumor progression in CRC tissues." (PMID 31652600, 2019).
MIR452 also shares sentences with these, for which no sentence is quoted: cancer (1 paper).